HK2 (hexokinase 2)
Diseases named in the same sentence as HK2 in open-access papers (continued):
Sharing a sentence is not in itself a finding about the gene and the disease.
prostate carcinoma (continued). "In prostate cancer (PCa), it has been shown to be driven by PTEN loss- and Akt hyperactivation-associated upregulation of hexokinase 2 (HK2)." (PMID 35563663, 2022). "EZH2 upregulation in prostate cancer cells results in the induction of hexokinase-2 (HK2) to increase glycolysis." (PMID 35236381, 2022). "MiRNA-181b as a tumor-suppressor factor binds to 3′-UTR of HK2 to inhibit glycolysis and progression of prostate cancer cells." (PMID 35236381, 2022). "HK2 has also been shown to be the ubiquitin target in prostate cancer cells through the covalent binding of the ubiquitin E3 HectH9." (PMID 33753739, 2021). "Taken together, our data provide evidence of SUMO modification of HK2 and an outline of the related mechanism, shedding light on alternative strategies for prostate cancer therapy." (PMID 33753739, 2021). "For example, in prostate cancer cells, androgen increases glucose utilization via activation of HK2." (PMID 34680657, 2021). "HK2 is the most investigated HK family member and has been identified as a tumor promoter in various cancers, such as gallbladder, liver, and prostate cancer." (PMID 34145399, 2021). "HectH9 promotes HK2 ubiquitination and regulates HK2 localization to the mitochondria in prostate cancer stem cells." (PMID 33753739, 2021). "To verify HK2 SUMOylation in prostate cancer cells, we used PC3, which contains high levels of endogenous HK24, to perform a coimmunoprecipitation assay." (PMID 33753739, 2021). "Lectins, in particular Polygonatum cyrtonema lectins (PCL), were also able to trigger apoptosis in prostate cancer cells targeting HK2, leading to decreased glucose consumption and lactate production." (PMID 34944758, 2021). "Here, the authors show that SUMOylation of hexokinase 2 disrupts its binding to mitochondria and protects cells from tumorigenesis in prostate cancer." (PMID 33753739, 2021). "Accumulating evidence shows that prostate cancer undergoes metabolic reprogramming and that HK2 is required for this process." (PMID 33753739, 2021). "Our data provide evidence for a previously uncovered posttranslational modification of hexokinase 2 in cancer cells, suggesting a potentially actionable strategy for preventing chemotherapy resistance in prostate cancer." (PMID 33753739, 2021). "HK2 was regulated by the circ‐ZNF609/miR‐501‐3p axis in prostate cancer cells, which affected the survival, metastasis, radiation resistance and apoptosis of prostate cancer cells." (PMID 34697887, 2021). "Mabjeesh et al71 showed that detection of mRNA of PSA and hK2 transcripts by polymerase chain reaction (PCR) in the peripheral blood of patients with prostate cancer during brachytherapy can predict the biochemical outcome." (PMID 33490732, 2021). "In this study, we aimed to explore the role of HK2 SUMOylation in the modulation of its subcellular trafficking, especially during chemotherapy in prostate cancer." (PMID 33753739, 2021). "ZNF609 promotes radioresistance by enhancing the glycolysis through miR-501-3p/HK2 signaling in prostate cancer." (PMID 34520391, 2021). "Among 324 men prescreened with PSA for prostate cancer and referred for biopsy, patients with hK2 measurements within the highest quartile had a 5- to 8-fold increase in risk for prostate cancer." (PMID 33490732, 2021). "Human Kallikreins other than PSA, such as free PSA, intact PSA and hK2, are the most used reflex tests for this purpose and are included in the currently available blood-based test for prostate cancer screening." (PMID 33807333, 2021). "EZH2 can promote the development and evolution of prostate cancer by regulating HK2-mediated tumor anaerobic glycolysis." (PMID 33299646, 2020).
prostate carcinoma (continued). "It has been reported that HK2 can be amplified into two different fragments through alternative splicing and influence the invasion and metastasis of prostate cancer." (PMID 33101378, 2020). "The risk of prostate cancer has been reported associated with single-nucleotide polymorphisms (SNPs) located in the genes coding for PSA (KLK3) and hK2 (KLK2)." (PMID 31639059, 2019). "Here, the authors show that in prostate cancer models, the ubiquitin ligase Hect9 promotes tumor growth by accelerating glucose metabolism via ubiquitination of Hexokinase 2, a central regulator of glycolysis." (PMID 31201299, 2019). "In this study, we introduce a strategy that takes advantage of the oncoaddiction of prostate cancer to AR—and its upregulation following DNA damage—by radioimmunotherapy targeting of human kallikrein peptidase 2 (hK2)." (PMID 29691406, 2018). "We therefore examined the human prostate cancer cell lines DU145, PC3, and LNCaP for expression of HK2 and found that the PTEN-deficient PC3 and LNCaP cells expressed higher levels of HK2 compared with the PTEN-proficient DU145 cells." (PMID 29687779, 2018). "Overexpression of either the HK1 or HK2 has been detected in many tumors, including breast, colon and prostate cancers, cervical carcinoma, gastric adenoma, glioma and lymphoma." (PMID 29721175, 2018). "We concluded that HK2 is required for prostate cancer development and that its deletion induces both cytostatic and cytotoxic effects." (PMID 29687779, 2018). "As systemic HK2 deletion is tolerated in mice, HK2 inhibition is a viable approach to circumvent chemoresistance induced by Akt activation in prostate cancer." (PMID 29687779, 2018). "In humans, salivary gland tissue immunostaining towards hK2, though positive, has been shown to be considerably less intense than that of the prostate and prostate carcinoma." (PMID 26983637, 2016). "In this study, we have demonstrated the therapeutic efficacy of 177Lu-m11B6, a hK2-targeting radioimmunoconjugate, in prostate cancer xenografts." (PMID 26983637, 2016). "We have proven the possibility of radioimmunotherapy targeting hK2 in subcutaneous prostate cancer xenografts." (PMID 26983637, 2016). "Since the expression of hK2 protein is higher in malignant prostatic tissue versus benign tissue it has been also considered as a prostate cancer (PCa) biomarker since levels of hK2 in serum from PCa patients are increased relative to individuals with BPH." (PMID 26007739, 2015). "The biology of prostate cancer, particularly, the shared androgen dependence of PSA and hK2, taken together with our previous work adds to the mounting evidence that KLK2 is a prostate cancer susceptibility gene." (PMID 25279276, 2014). "Overall most relevant studies concluded that hK2 has additive role in the detection of prostate cancer." (PMID 24809052, 2014). "As they are also expressed in prostate tissue and are closely related to PSA and hK2, the other members of the tissue kallikrein family have also been investigated upon for their potential role in the detection and prognosis of prostate cancer." (PMID 24809052, 2014). "We have, for the first time, incorporated hK2 levels with a novel SNP to enhance the prediction of prostate cancer in this setting." (PMID 25279276, 2014). "Serum hK2 levels were significantly higher among cases (mean hK2 = 0.246 ng/mL) than controls (mean hK2 = 0.228 ng/mL, p = 0.02), and the rs198977 KLK2 SNP was significantly associated with prostate cancer." (PMID 25279276, 2014). "Similar results were found for the other kallikreins: all but hK2 (p = 0.06) remained statistically significant predictors of advanced prostate cancer among men diagnosed at least 20 years after venipuncture." (PMID 18279502, 2008).
prostate carcinoma (continued). "Furthermore, PCL also exerted anti-metastatic effects by inhibiting tumor cell aggregation and suppressing glycolysis in PC3 prostate cancer cells with bone metastasis, primarily through downregulation of hexokinase 2 (HK2), a key enzyme in the Warburg effect." (PMID 41293256, 2025). "Phase 1 studies assessing hK2-targeting therapies, including 225Ac radioimmunotherapy, are currently ongoing and may further support hK2 as a therapeutic target in advanced prostate cancer." (PMID 38782459, 2024). "Using AR‐positive prostate cancer cell lines, we showed that MA inhibited AR expression in LNCaP and 22Rv1 cell lines, including AR‐regulated proteins prostate‐specific antigen (PSA) and human kallikrein 2 (hK2), and the AR‐V7 variant in 22Rv1 cells." (PMID 38605607, 2024). "In addition to this, circ-ZNF609 also enhances the viability, migration, and invasion of prostate cancer cells through the miR-501-3p/HK2 axis, while hindering the apoptosis of prostate cancer cells." (PMID 36142355, 2022). "Lys63-linked non-proteolytic ubiquitination of Hexokinase 2 by HectH9 effectively disrupts glycolysis activation and facilitates apoptosis in prostate cancer cells." (PMID 35874839, 2022). "In the PtenPC−/−/Tp53PC−/− prostate cancer mouse model, HK2 is required for tumorigenesis." (PMID 33753739, 2021). "Moreover, we demonstrate an inverse relationship between SENP1-hexokinase 2 axis and chemotherapy response in prostate cancer samples." (PMID 33753739, 2021). "We sought to assess the potential effect of HK2 SUMOylation on prostate cancer patient prognosis." (PMID 33753739, 2021). "All these data demonstrate that SUMO-defective HK2 might contribute to prostate cancer cell proliferation and oncogenesis." (PMID 33753739, 2021). "Further, mTORC1 promotes glycolysis by increasing HK2 translation in prostate cancer cells." (PMID 33052246, 2020). "Indeed, co-immunoprecipitation assays revealed endogenous interaction between HectH9 and HK2 in prostate cancer cells." (PMID 31201299, 2019). "Moreover, HectH9 depletion inhibited the lactate production and ECAR to a similar degree as HK2 knockdown in prostate cancer cells." (PMID 31201299, 2019). "The transgenic cancer susceptible mouse with prostate specific expression of human hK2 (Hi-Myc x pb_KLK2) recapitulates the biology of human prostate cancer and was engineered to investigate the radiobiological mechanisms that are the design foundation for [225Ac]hu11B6." (PMID 29691406, 2018). "Levels of total human kallikrein 2 (hK2), a protein involved the pathology of prostate cancer (PCa), could be used as a biomarker to aid in the diagnosis of this disease." (PMID 26007739, 2015). "Since our assay can detect one or two orders of magnitude lower amounts of hK2 compared to the highly optimized ELISA system it could contribute to future clinical practice by enabling more accurate diagnosis of prostate cancer patients." (PMID 26007739, 2015). "111In-DTPA-11B6 is a new radiotracer for SPECT/CT imaging of hK2-expressing prostate cancer." (PMID 26116115, 2014). "Of these, approaches to measure distinct molecular forms of PSA (free, intact, complexed PSA, and pro-PSA) combined with kallikrein-related peptidase 2 (KLK2), also known as hK2, have been considered holding particular promise in enhancing the diagnosis of prostate cancer." (PMID 24809052, 2014). "KLK2 protein (hK2), is also considered as a secondary marker of prostate cancer." (PMID 23587030, 2013). "This type of protease inhibitor has been reported to form complexes with the kallikrein family such as hK3 (also known as a prostate-specific antigen), hK2 and hK6, and could be applied in the diagnosis of prostate cancers." (PMID 22363757, 2012). "Prostate-specific antigen, also known as hK3, and its molecular forms are the most useful tumour markers for the prostate cancer and hK2, another member of the kallikrein gene family, may help in reducing the number of unnecessary biopsies." (PMID 12671711, 2003).
prostate carcinoma (continued). "Moreover, our study extends the role of HK2 in docetaxel response in prostate cancer chemotherapy." (PMID 33753739, 2021). "Moreover, our histological analyses showed that HK2 protein is upregulated in prostate cancer." (PMID 31201299, 2019). "We examined whether hK2 protein and gene SNPs predict prostate cancer at the time of repeat biopsy." (PMID 25279276, 2014). "A previous study has shown that under hypoxia conditions, HK2, LDHA, and glucose transporter 1 (GLUT1) are upregulated in prostate cancer cells, and brusatol treatment inhibits glycolysis by decreasing the expression of these glycolysis-related enzymes." (PMID 41214670, 2025). "Since the roles of hypoxia-induced HK2 in prostate cancer cells have been widely reported, we mainly focused on FOXD1, and HK2 was only detected as a key glycolytic enzyme in the following experiments." (PMID 41214670, 2025). "This first-in-human phase 0 trial uses an 111In-radiolabeled anti-hK2 monoclonal antibody, [111In]-DOTA-h11B6, to credential hK2 as a potential target for prostate cancer treatment." (PMID 38782459, 2024). "Subsequent to XHP treatment, the protein expression levels of HIF-1α, GLUT1, HK2, and PKM2 in both prostate cancer tissues and the two cell lines showed a significant reduction." (PMID 38994113, 2024). "Prostate cancer is rich in tumor associated antigens such as, but not limited to, PSMA, PSCA, hK2, and STEAP1 and there is strong biologic rationale for employment of T-cell redirecting BiTEs within the prostate cancer disease space." (PMID 38801069, 2024). "Previous studies in prostate cancer have also shown that miR-143-3p can inhibit cell growth through various targets, including KRAS, Bcl-2, ERK5, LIMK1, HK2 and KLK2." (PMID 37759434, 2023). "The high expression of NPAS2 promotes the release of HIF-1A and key glycolytic genes (HK2, PKM2, GLUT1 and MCT4), enhancing glycolytic metabolite levels, thus inducing the progression of prostate cancer cells." (PMID 36978001, 2023). "Serum hK2 levels, used in addition to PSA, have been shown to enhance discrimination between patients with benign prostate disease and those with prostate cancer." (PMID 33490732, 2021). "Immunofluorescent staining illustrated that the majority of HK2 emerged in a punctuate distribution and was co-localized with VDAC in prostate cancer cells." (PMID 31201299, 2019). "Among the glycolytic genes, we found the down-regulation of MPC1 (BRP44L), and the up-regulation of HK2 and GPI in prostate cancer, which also showed similar dysregulation patterns in other types of cancers." (PMID 26895100, 2016). "Our past studies demonstrated that hexokinase-2 (HK2) and Golgi membrane protein 1 (GOLM1) were directly regulated by miR-143 and miR-145-5p in renal carcinoma and prostate cancer, respectively." (PMID 27072587, 2016). "In prostate cancer cells, TNC expression is significantly positively correlated with the expression levels of key glycolytic enzymes, such as glucose transporter 1 and hexokinase 2 (HK2)." (PMID 40046232, 2025). "The expression levels of HK2 and FOXD1 mRNA were both increased in cancer group compared to those in normal group, and HK2 and FOXD1 mRNA levels were both increased after hypoxic treatment in prostate cancer PC-3, 22Rv1, DU145, and LNCaP cells." (PMID 41214670, 2025). "Suppressing TNC expression through siRNA decreases glucose uptake and lactate production in the prostate cancer cell lines DU145, PC3, and LNCaP, while substantially decreasing the protein levels of the glycolytic enzymes HK2, LDHA, and pyruvate kinase isozyme M2 (PKM2)." (PMID 40046232, 2025).
prostate carcinoma (continued). "Similarly, knockdown of phospholipase C-ε suppresses hypoxia-induced increase in the expression of HK2, LDHA, and GLUT1 in some types of prostate cancer cell lines." (PMID 41214670, 2025). "Although hK2 alone is a relatively weak screeningmarker for prostate cancer it is relatively independent of PSA so the twotogether yield a better test than PSA alone." (PMID 35255236, 2022). "In summary, high expression of both HK2 and SENP1 might predict poor outcomes in prostate cancer patients." (PMID 33753739, 2021). "However, K315/492R mutation led to increased glucose uptake and lactate production in different prostate cancer cells, demonstrating that SUMO-defective HK2 enhances glycolytic flux in prostate cancer cells." (PMID 33753739, 2021). "Subsequently, several groups reported that %hK2 contributed to an enhanced discrimination between prostate cancer and noncancer patients." (PMID 24809052, 2014). "HK2 localization to mitochondrial surface is further promoted through the ubiquitination of the Lys-63 residue by HECTH9 E3 ligase, which elicits HK2 binding to VDAC on the OMM and the consequent expansion, metabolic rewiring and chemoresistance of cancer stem cells in a prostate cancer model." (PMID 33946854, 2021). "In human prostate cancer, deguelin treatment directly decreased c-Myc expression, which implied that in NSCLC, other molecular or signaling pathways may also involve in deguelin-induced HK2 or glycolysis suppression." (PMID 28427230, 2017). "This study addressed a recent suggestion that there may be differential regulation of seminal analytes in men after vasectomy; among 1,469 men without prostate cancer, we found little evidence that vasectomy is associated with different blood plasma concentrations of PSA variants or hK2." (PMID 28375714, 2017).